RNU6-632P (RNA, U6 small nuclear 632, pseudogene)
Gene: Small nuclear RNA gene on chromosome 10 (25,819,363 to 25,819,426, reverse strand). Ensembl gene ENSG00000251711.
Homologues: Orthologues: chimpanzee U6 (97% identical), macaque U6 (97% identical), pig U6 (88% identical), rat LOC120093902 (83% identical), mouse Gm24410 (81% identical), dog U6 (75% identical). Paralogues in human: RNU6-16P (91% identical), RNU6-340P (91% identical), RNU6-38P (91% identical), RNU6-1106P (89% identical), RNU6-1145P (89% identical), RNU6-1181P (89% identical), RNU6-1304P (89% identical), RNU6-333P (89% identical), RNU6-393P (89% identical), RNU6-510P (89% identical), RNU6-532P (89% identical), RNU6-537P (89% identical), and 1285 more.